EGR1 (early growth response 1)
Diseases named in the same sentence as EGR1 in open-access papers (continued):
Sharing a sentence is not in itself a finding about the gene and the disease.
atherosclerosis (continued). "Egr-1/MCP-1 interplay plays an important role in promoting atherogenic lipids (OxLDLs) initiating monocyte infiltration and adhesion during atherosclerosis." (PMID 22135674, 2011). "Our results provide novel insights into the regulatory role of dietary ω-6 lipids on two of the major transcription factors that are relevant to atherosclerosis, PPAR, and Egr-1 with differing vascular effects." (PMID 22135674, 2011). "Egr-1 signaling, PI3K or PKC might be interesting targets for drug therapy in atherosclerosis and diabetic disease in the future." (PMID 23202940, 2012). "In detail, the decrease in MAPK6 expression promotes the interaction between EGR1 and NF‐κB and ultimately accelerates the accumulation of NF‐κB in the nucleus, which promotes the transcription of CXCL12, thereby accelerating the progression of atherosclerosis." (PMID 39763069, 2025). "Fos and Egr1 are prototypic master regulators known as immediate early-genes (IEG) that orchestrate widespread activation of cellular gene expression in response to specific perturbations, including hypoxia, ischemia, atherosclerosis, angiogenesis, and neuronal survival." (PMID 21569252, 2011).
hepatocellular carcinoma (36 papers, 2012 to 2026). A malignant tumor that arises from hepatocytes. "MtRNA-seq identified nuclear-encoded EGR1 mRNA, an immediate-early gene, as notably enriched in hepatoma mitochondria." (PMID 41356200, 2026). "Yan and co-workers reported that hypoxia triggered Egr1 in cultured hepatoma-derived cells deficient in HIF-1β." (PMID 25375852, 2014). "Furthermore, downregulation of EGR1 has been associated to hepatocellular carcinoma (HCC) development." (PMID 31036066, 2019). "Together, these findings demonstrate that mitochondrial EGR1 ntmRNA is critical for regulating hypoxia-induced mitophagy in hepatoma cells." (PMID 41356200, 2026). "Given the essential role of mitochondrial EGR1 ntmRNA in mitophagy and mitochondrial function, we assessed the impact of EGR1 knockdown on malignant behaviors of hepatoma cells." (PMID 41356200, 2026). "miR-181a-5p inhibited the cellular malignant proliferation via repressing EGR1 in hepatocellular carcinoma." (PMID 36193503, 2022). "In hepatocellular carcinoma, EGR1 induces SLUG through the ERK–AKT–EGR1–SLUG signaling cascade and stimulates EMT of cancer cells." (PMID 33842351, 2021). "In hepatocellular carcinoma cells, EGR1 induced by hepatocyte growth factor (HGF) can directly bind to the promoter region of SNAIL, increase its expression, and lead to tumor cell metastasis." (PMID 33842351, 2021). "In this review article, we begin by discussing the role of Egr1 in liver metabolism, and then focus on Egr1 in pathological states of liver with a particular interest in hepatocellular carcinoma (HCC)." (PMID 29607419, 2017). "In this study, we found that the overexpression of EGR1 suppresses hepatocellular carcinoma cell proliferation and increases cell apoptosis by binding to the miR-203a promoter sequence." (PMID 27244890, 2016). "While killing hepatoma cells, 131I can activate Egr1 promotor to induce HSV-TK gene expression and the expression can be especially enhanced by HRE in hypoxic solid cancer, so the gene therapy can be initiated." (PMID 27642033, 2016). "Notably, EGR1 ntmRNA had minimal effects under normoxia, consistent with low basal mitophagy levels in hepatoma cells." (PMID 41356200, 2026). "In hepatocellular carcinoma, Egr-1 expression is induced by b-lapachone, which may hinder invasion and metastasis by impacting TSP1, SNAIL, and E-cadherin expression." (PMID 37046823, 2023). "In hepatocellular carcinoma, it has been demonstrated that β-lapachone induces the expression of EGR1, and the latter may suppress invasion and metastasis by affecting the expression of TSP1, SNAIL, and E-cadherin." (PMID 33842351, 2021). "Furthermore, Egr1 induces apoptosis in human hepatoma cells (HepG2 and Hep3B) that can be enhanced by synthetic chenodeoxycholic acid derivative, HS-1200." (PMID 29607419, 2017). "Additionally, apoptotic pathway analysis revealed increased expression of apoptotic markers (Cytochrome C, PARP, cleaved PARP, Caspase-3, cleaved Caspase-3, Bax) and decreased anti-apoptotic protein BCL-2 in EGR1-knockdown cells, indicating that EGR1 depletion promotes apoptosis in hepatoma cells." (PMID 41356200, 2026). "Consistently, the oncogenic role of SNHG16 in hepatocellular carcinoma was revealed in a study which demonstrated that this lncRNA promoted viability and autophagy but limited apoptosis to sustain resistance to sorafenib and these were collectively implemented through the axis of miR-23b-3p/EGR1." (PMID 36983973, 2023). "In hepatocellular carcinoma, CBX8 upregulates EGR1 and miR-365-3p to stimulate the AKT/β-catenin pathway and shows oncogenic activity." (PMID 34395271, 2021).
hepatocellular carcinoma (continued). "In hepatocellular carcinoma, SNHG16 is highly expressed in HCC-resistant tissues and promotes HCC cell viability and autophagy while suppressing apoptosis by regulating the miR-23b-3p/EGR1 pathway." (PMID 33435953, 2021). "Insulin regulates Egr1 expression in hepatoma cells and in non-liver-derived cells overexpressed with insulin receptors." (PMID 29607419, 2017).
schizophrenia (36 papers, 2013 to 2025). A major psychotic disorder characterized by abnormalities in the perception or expression of reality. "EGR1 has been linked to stress-related mood disorders, schizophrenia, and major depressive disorder." (PMID 35346959, 2022). "Deficient EGR1 mRNA expression was detected in schizophrenia and was correlated with significantly lower levels of GAD67." (PMID 32345355, 2020). "The regulatory relationships with schizophrenia-associated EGRs (EGR1 and EGR3) suggest a role for NAB2 in neuropsychiatric illness." (PMID 29520222, 2018). "In line with its crucial role in shaping neuronal response, EGR1 is associated with the etiology and treatment of most common neuropsychiatric disorders such as major depressive disorder, anxiety disorders, schizophrenia, or addiction." (PMID 28321184, 2017). "Indeed, the effect we describe in zebrafish induced by the egr1 mutation is consistent with the identification of EGR1 as a susceptibility gene for neuropsychiatric disorders including schizophrenia and depression." (PMID 35346959, 2022). "Finally, in the search for schizophrenia biomarkers in peripheral tissues, EGR1 levels in whole blood samples was associated with schizophrenic symptoms such as high delusional states." (PMID 28321184, 2017). "As for the association between the SKIL and schizophrenia, a previous study used the network coexpression analysis in three microarray datasets, and established a miRNA-TF-gene network related to schizophrenia, including the EGR1-miR-124-3p-SKIL feed-forward loop." (PMID 35136033, 2022). "Studies in mouse and zebrafish models demonstrated an important role for Egr1 in social behavior and the formation of proper neuronal circuits, while in humans Egr1 was shown to be connected with stress-related mood disorders, schizophrenia, and depression." (PMID 37234916, 2023). "Dysregulation in IEGs has been implicated in many neurological diseases, including increased circulating Egr1 in schizophrenia, increased Arc in the amygdala in major depressive disorder, and increased cFos and cJun in the hippocampus and amygdala in AD." (PMID 36732588, 2023). "They further suggested that Egr 1 gene downregulation can be related to various neurological disorders like Schizophrenia." (PMID 35107124, 2022). "A genome-wide association study found that six immune candidates, namely, DPP4, HSPD1, EGR1, CLU, ESAM, and NFATC3, were associated with schizophrenia." (PMID 35757702, 2022). "Early growth response protein 1 (EGR-1) and activity-dependent cytoskeleton-associated protein (ARC) are two immediate early genes associated with schizophrenia." (PMID 36233357, 2022). "Altered EGR1 expression patterns have been documented in humans with neuropsychiatric disorders, like schizophrenia, where decreased EGR1 expression in the dorsal lateral prefrontal cortex is thought to contribute to patient symptoms." (PMID 36338037, 2022). "A decreased EGR1 gene expression because of EGR1 methylation has been reported in schizophrenia patients." (PMID 34831111, 2021). "The downregulation of EGR1 has been reported in the blood and prefrontal cortex of schizophrenia patients." (PMID 34831111, 2021). "A decrease in the EGR1 expression in the peripheral blood and prefrontal cortex of patients with schizophrenia has been reported." (PMID 34831111, 2021). "In particular, in neuropsychiatric disorders, such as depression, anxiety, and schizophrenia, EGR1 levels are lower in female- and brain site-specific manner when compared to healthy controls." (PMID 33198374, 2020). "A previous study of GEO datasets GSE62333 also reported the up-regulation of FOSB and FOS in the fibroblasts of schizophrenia patients and mainly focused on EGR1 and other genes as biomarkers for disease diagnosis." (PMID 30967896, 2019).
schizophrenia (continued). "Despite the paucity of published work on the role of NAB2 in the brain, the regulatory relationships between NAB2, EGR1 and EGR3 link this gene not only to other specific schizophrenia-associated genes, but also to the proposed pathway for illness association." (PMID 29520222, 2018). "In particular, the two studies reporting reduced peripheral blood cell levels of EGR1 were examining schizophrenia patients during an acute psychotic episode, while the other study did not specify the patients’ current symptom status." (PMID 29520222, 2018). "They used this 7-miRNA signature to distinguish the schizophrenia patients from the normal controls and an AUC of 0.93 was determined using the ROC analysis, which is close to ours (0.962 for the EGR1-miR-30a-5p-NEUROD1 axis)." (PMID 28072411, 2017). "Altogether, these findings support a role for EGR1 in both the etiology and therapeutic interventions in schizophrenia." (PMID 28321184, 2017). "Clinical studies have reported an abnormal regulation of Egr1 in schizophrenia patients compared to normal controls." (PMID 29321734, 2017). "Transcriptional changes were assessed in an independent cohort, revealing the transcription factor EGR1 as significantly down-regulated in both cohorts and as a potential regulator of broader transcription changes observed in schizophrenia patients." (PMID 28754123, 2017). "Although EGR1 levels are altered in various disorders including schizophrenia, it is important to note that mutations in the human population have not yet been identified which directly link EGR1 and these disorders." (PMID 35346959, 2022). "An upregulation of EGR1 has been found in the fibroblast and blood of schizophrenia patients." (PMID 34831111, 2021). "This suggests an involvement of EGR1 gene in the development of schizophrenia." (PMID 34831111, 2021). "EGR3 binds to NAB2 to co-regulate expression of target genes, and is involved in co-regulatory feedback relationships with EGR1, as well EGR1, EGR2 and EGR3 can regulate NAB2 expression, demonstrating a functional interaction of both of these schizophrenia associated genes in the proposed pathway." (PMID 29520222, 2018). "Finally, Egr1 levels of expression have been recently investigated in preclinical settings exploring new therapeutic strategies in schizophrenia beyond current antipsychotic drugs." (PMID 29321734, 2017). "Meanwhile, some questions remain to be answered: first, it has been reported that EGR1 expression is also downregulated in the prefrontal cortex from patients with schizophrenia, we strongly felt the EGR1-miR-30a-5p-NEUROD1 axis has a role in the pathogenesis of schizophrenia." (PMID 28072411, 2017). "In this context, a similar dysregulation of EGR1 expression is observed in other neuropsychiatric disorder characterized by functional alterations in PFC activity such as schizophrenia, where Egr1 mRNA levels are also found down-regulated in the dorsolateral prefrontal cortex." (PMID 28321184, 2017). "Furthermore, it has been shown that PACAP-induced neuritogenesis depends on up-regulation of Egr1 expression, a member of the EGR gene family involved in regulation of synaptic plasticity, learning, and memory, and implicated in schizophrenia pathogenesis." (PMID 25807538, 2015). "In a mouse model of maternal influenza viral infection, which is a risk factor for schizophrenia, an adult-onset abnormal response to DOI is observed, with an exaggerated head-twitch response and expression of the genes c-fos, egr-1 and egr-2 in cortical neurons." (PMID 24586556, 2014). "Indeed, EGR1 has also been widely reported to be a major regulator of synaptic plasticity in different neurons and brain regions, including the cerebellum, in physiological and pathological conditions such as schizophrenia." (PMID 40332239, 2025). "In addition, Egr1 is known to have a decreased expression in the brains of schizophrenia patients." (PMID 37928724, 2023).
schizophrenia (continued). "The behavioral changes were accompanied by increased early growth response protein 1 (EGR-1) and activity-dependent cytoskeleton-associated protein (ARC) levels in the sensorimotor cortex and hippocampus, regions implicated in circuitry dysfunction in schizophrenia." (PMID 36233357, 2022). "In this context, it is noteworthy that several lines of evidence point towards a role of EGR-1 and ARC in schizophrenia, and that was why we decided to focus our studies on these two immediate early genes." (PMID 36233357, 2022). "EGR3 interacts in regulatory feedback loops with other EGR-family genes in the immune system, including EGR1, EGR2, EGR4 and NAB2, each of which maps to GWAS loci for schizophrenia." (PMID 35941129, 2022). "We previously reported the genetic association of EGR3 with schizophrenia and downregulation of the transcripts for EGR1, EGR2, and EGR3 in the postmortem brain samples from patients with schizophrenia." (PMID 33656268, 2021). "The genes HGF, PRRT2, EGR1, EGR3, C11orf87, TLR3 and PLEKHH2 have been reported in either genetic analysis or gene expression analysis of schizophrenia, and were all upregulated in fibroblasts from patients in our study." (PMID 31959813, 2020). "ZFHX3, RND3, KLF5, ERBB4, EGR1 and APC genes are both schizophrenia candidate genes and tumor suppression genes." (PMID 24564241, 2013). "Moreover, the downregulation of EGR1, EGR2, and EGR3 transcripts was reported in the postmortem brains of patients with schizophrenia." (PMID 39518903, 2024). "Their real-time quantitative PCR analysis illuminated patients with schizophrenia have the overexpression of miR-124-3p, the under expression of SKIL and EGR1 in the blood compared with controls, and after a 12-week treatment, the direction of change of miR-124-3p and SKIL mRNA levels were reversed." (PMID 35136033, 2022). "A change in early growth response 1 (EGR1) expression has been derived from the aberrant methylation of the EGR1 gene promoter region in schizophrenia, and increased ERG1 expression might be connected with the pathophysiology of schizophrenia." (PMID 34136553, 2021). "Additional proteins implicated in risk for schizophrenia, but that have not yet been reported to affect LTD, interact with this pathway either as upstream activators (e.g., NRG1) or as transcriptional regulators (e.g., EGR1 and NAB2)." (PMID 29520222, 2018).
cardiac hypertrophy (30 papers, 2011 to 2025). "It is worth noting that several known proteins associated with myocardial hypertrophy, such as Myc, Fos, and Egr1, were present at the center of the network." (PMID 35211156, 2022). "Interestingly, we identified four genes, Btg2, Egr1, Fos, and Atf3, associated with cardiac hypertrophy, in overlapping DEGs between the upregulated DEGs in PAH versus control groups and the downregulated DEGs in PAH/αKO versus PAH groups." (PMID 36736425, 2023). "Additionally, Nab1, a repressor of EGR, has been shown to be a potent inhibitor of pathological cardiac hypertrophy and EGR1 deficient mice have a blunted catecholamine-induced hypertrophy response and are more sensitive to stress." (PMID 26011708, 2015). "Acetate downregulates the expression of early growth response-1(Egr-1, a kind of transcription factor) in the heart and kidneys, a critical factor involved in cardiac hypertrophy, cardiorenal fibrosis, and inflammation." (PMID 40709198, 2025). "Direct reductions in acute inotropy is thought to be mediated by GPCR43, with more chronic changes mediated by SCFA-mediated downregulation of Egr1—a cardiovascular regulator gene involved in cardiac hypertrophy." (PMID 40676310, 2025). "Cardiac-specific NAB1 overexpression regulates cardiomyocyte growth through interaction with Egr-1 and inhibits cardiac hypertrophy in response to pressure overload." (PMID 39619154, 2024). "In particular, we demonstrated that the SP1 inhibitor plicamycin and the EGR1 inhibitor ML264 had therapeutic effects on attenuating cardiac hypertrophy in an HCM mouse model, possibly by reversing fetal reprogramming." (PMID 38780967, 2024). "These previous reports underpinned a crucial role for EGR1 in cardiac hypertrophy, and the results obtained in the current study further expanded the field of action of EGR1 to cardiac hypertrophy resulting from PH." (PMID 35625405, 2022). "Among these, Egr1 in cluster J4, which is involved in angiogenesis, cardiac hypertrophy, and cardioprotection, demonstrated significantly decreased expression at P7 and P14 in the Sox6 KO hearts compared to control." (PMID 27832192, 2016). "For example, we observed deregulation of chamber-specific factors (e.g. Myh7, Bmp7, Anf, Acta1, Egr1 and Fos) that are also upregulated in adult cardiac hypertrophy and/or heart failure." (PMID 25803368, 2015). "Indeed, we found that the inhibition of SP1 and EGR1, which are newly found TFs with fetal chromatin accessibility patterns in patients, markedly repressed cardiac hypertrophy in HCM mice and thus provided potential drug targets for HCM treatment." (PMID 38780967, 2024). "Thus, we verified the expression of the fetal phenotype and atrophy-related marker Tgfb2 and the markers of cardiac hypertrophy Egr1 and Ccna2." (PMID 37108224, 2023). "The positive biological effects of fibers and acetate were ascribed to: (i) the downregulation of cardiac and renal genes for early-growth-response-protein-1 (Egr1), involved in myocardial hypertrophy, fibrosis, and inflammation; (ii) the downregulation of the renin–angiotensin system in the kidney." (PMID 35743626, 2022). "Furthermore, Egr1 played an important role in the early stages of cardiac hypertrophy via transcriptional regulation of T-type calcium channels, and Egr1 was reported as an endogenous regulator of pathologic cardiac hypertrophy." (PMID 35625405, 2022). "However, in the cardiac stress overload model, Egr1 was been studied in the context of myocardial hypertrophy." (PMID 35799890, 2022). "For example, EGR1 is a downstream effector in atherosclerosis, angiogenesis, and cardiac hypertrophy, and has been shown to regulate gene expression in vascular smooth muscle downstream of mechanical stretch, a stimulus that modulates costamere/focal adhesion activity." (PMID 26011708, 2015).